METTL3 (methyltransferase 3, N6-adenosine-methyltransferase complex catalytic subunit)
Diseases named in the same sentence as METTL3 in open-access papers (continued):
Sharing a sentence is not in itself a finding about the gene and the disease.
breast cancer (continued). "METTL3 has been demonstrated to be a Let-7g-specific target in breast cancer." (PMID 35008539, 2021). "Our findings suggest that METTL3 may be considered as a potential therapeutic target of metformin for breast cancer." (PMID 33431790, 2021). "Moreover, p21 is the main target of METTL3 in the breast cancer proliferation inhibitory effect of metformin." (PMID 33431790, 2021). "Moreover, METTL3 was upregulated in breast cancer cells, compared with that in the normal breast epithelial cell lines MCF-10A and HBL-100 in both mRNA and protein levels." (PMID 33431790, 2021). "Furthermore, we explored the target gene p21 of METTL3 and revealed the mechanism of modulating p21 in breast cancer." (PMID 33431790, 2021). "Metformin could reduce the m6A level via decreasing METTL3 expression mediated by miR-483-3p in breast cancer." (PMID 33431790, 2021). "Through bioinformatic analysis and verified experiments, we focused on miR-483-3p as a possible target microRNA of metformin and an upstream microRNA of METTL3, suggesting that metformin inhibited the proliferation of breast cancer cells by the miR-483-3p/METTL3 pathway." (PMID 33431790, 2021). "Our findings suggest that METTL3 may be considered as a novel potential therapeutic target of metformin for breast cancer." (PMID 33431790, 2021). "Elevated level of METTL3 was found in clinical samples from breast cancer patients." (PMID 32194861, 2020). "METTL3 acts as a tumor suppressor in renal cell carcinoma, while METTL3 promotes chemo‐ and radioresistance in pancreatic cancer cells and promotes breast cancer progression." (PMID 31670863, 2020). "Consistently, overexpression of HBXIP could extensively emancipate the hindered proliferation and enhanced apoptosis driven by METTL3 silencing in breast cancer cells." (PMID 33048840, 2020). "In this study, we used Oncomine and The Cancer Genome Atlas (TCGA) databases to jointly analyze the expression of m6A “writer” in breast cancer including METTL3, METTL14, WTAP, RBM15, RBM15B, and ZC3H13, indicating that the mRNA expression levels of METTL14 and ZC3H13 were lower in tumor samples." (PMID 33363011, 2020). "Finally, with immunohistochemistry staining in breast cancer tissues, it was proved that METTL3 expression was negatively correlated with COL3A1 in TNBC, but not in non-TNBC." (PMID 32766145, 2020). "Recent studies showed that METTL3 was upregulated in breast cancer tissue and cells." (PMID 31921660, 2019). "In addition, the Cancer Genome Atlas (TCGA) data analysis revealed that METTL3 was upregulated in multiple cancers, including liver cancer, breast cancer, colorectal cancer, prostate cancer, and bile duct cancer." (PMID 31757221, 2019). "METTL3 recognizes the pri-miRNAs by microprocessor protein DGCR8 and causes the elevation of mature miRNAs and concomitant reduction of unprocessed pri-miRNAs in breast cancer." (PMID 31142332, 2019). "HBXIP is highly expressed in breast cancer and can upregulate METTL3 expression." (PMID 31757221, 2019). "Our findings revealed the downregulation of LINC01133 in ER+ breast cancer and provided novel insight to the role of METTL3/YTHDF2/LINC01133/IGF2BP2 axis in ER+ breast cancer, which might offer a novel perspective in the design and development of novel anticancer drugs." (PMID 40641925, 2025). "Moreover, silencing of METTL3 significantly reduced m6A modification in breast cancer (BC) cells, decreased PD-L1 mRNA stability, and inhibited PD-L1 expression via the m6A-IGF2BP3 axis, enhancing antitumor immunity by promoting T cell activation, infiltration, and reducing exhaustion." (PMID 39987091, 2025). "However, the roles of METTL14 and METTL3 in breast cancer, in general, are controversial." (PMID 38545841, 2024). "It has been reported that Sox2 could be m6A modified by METTL3 in the breast cancer." (PMID 36977205, 2023).
breast cancer (continued). "GO analysis revealed that the common METTL3-regulated AS events in breast cancer cell lines were enriched for the terms “translation”, “regulation of apoptotic process” and “regulation of growth”, suggesting that METTL3 may affect breast tumorigenesis through AS regulation." (PMID 36725888, 2023). "Moreover, we examined the protein level of METTL3 in six different breast cancer cell types." (PMID 36609396, 2023). "The ablation of METTL3 caused apoptosis and reduced the invasiveness of lung adenocarcinoma cells, whereas hypoxia-activated m6A demethylase ALKBH5 induces the accumulation of breast cancer stem cells through HIF-dependent and ALKBH5-mediated m6A demethylation of NANOG mRNA." (PMID 37391814, 2023). "Therefore, METTL3 may make breast cancer cells resistant to doxorubicin through the miR-221-3p/HIPK2 axis." (PMID 37264402, 2023). "However, the immunohistochemistry (IHC) results conducted in breast cancer tissue microarrays (129 breast cancer tissue samples and three normal breast tissue samples) revealed that Mettl3 was expressed mostly in the cytoplasm and nuclei of cancer tissues, with a few expression in the cell membrane." (PMID 36609396, 2023). "Therefore, we assumed that METTL3 might regulate LINC00662 to induce docetaxel resistance of breast cancer." (PMID 36202872, 2022). "Expression levels of METTL3 in the tumor also negatively correlated with breast cancer (BC) patient survival rate and tumor-infiltrating CD8+ T cells, helper T cells, and activated NK cells." (PMID 35296338, 2022). "The identification of a feedback activation loop between IL-6 signaling and nuclear METTL3 function, which can be blunted by aspirin and nicotinamide co-treatment, unravels a critical interplay between inflammatory/oncogenic insults and RNA epigenetic state, which expedites breast cancer metastasis." (PMID 36289222, 2022). "Therefore, we investigated whether microRNAs play a vital role in breast cancer tumorigenesis by affecting METTL3 expression." (PMID 36077054, 2022). "Importantly, ADAR1 and METTL3 are two types of the most popular RNA modification events affecting adenosines, which motivated us to explore whether ADAR1 plays a role in breast cancer progression by regulating METTL3." (PMID 36077054, 2022). "Furthermore, the tight connection between METTL3 acetylation and node metastasis indicates that targeting METTL3 deacetylation by ASP/NAM may provide therapeutic advantages in breast cancer patients with node metastasis." (PMID 36289222, 2022). "Also, METTL3 was reportedly upregulated in breast cancer cells and tissues, with gene silencing significantly inhibiting cell proliferation and promoting apoptosis by regulating Bcl-2, thereby indicating an oncogenic role for METTL3 in breast cancer progression." (PMID 35096816, 2021). "METTL3 might be a therapeutic target, regarding its oncogenic role in breast cancer." (PMID 33431790, 2021). "In breast cancer, let-7g, as a tumor suppressor, was found to downregulate the expression of METTL3 by targeting the 3′-UTR of METTL3 mRNA, while hepatitis B virus X-interacting protein (HBXIP) could increase the expression of METTL3 by inhibiting the function of let-7g." (PMID 34108450, 2021). "Furthermore, CCK-8 and colony formation assay showed that miR-483-3p mimic could inhibit the growth of breast cancer cells, and overexpression of METTL3 rescued the growth inhibitory effect of miR-483-3p among breast cancer cell lines." (PMID 33431790, 2021). "METTL3, the pivotal methyltransferase of RNA m6A modification, was indicated involved in the initiation and development of different types of cancer, including lung cancer 21, colon cancer 21, breast cancer 22, liver cancer 23, myeloid leukemia 15 and bladder cancer." (PMID 32284755, 2020). "Moreover, the decrease of METTL3 in breast cancer has been noted." (PMID 32612834, 2020).
breast cancer (continued). "However, it would also be informative to investigate the role of ZNF217 in our HMEC-based system to see if it interacts with METTL3 and the m6A system and whether that interaction is regulated during breast cancer progression." (PMID 30131850, 2018). "Therefore, mutual regulation between HBXIP and METTL3 promotes progression of breast cancer." (PMID 30149601, 2018). "For example, overexpression of METTL3 enhances cell proliferation and resistance to chemotherapy, while ALKBH5-driven demethylation of pluripotency genes promotes breast cancer stemness." (PMID 41373981, 2025). "Numerous studies have demonstrated that m6A regulatory factors, including METTL3, METTL14, and ALKBH5, play pivotal roles in breast cancer cells, affecting cell proliferation, metastasis, and drug resistance." (PMID 39972939, 2025). "METTL3 can also target GPX4 by introducing m6A modification on its mRNA, increasing its mRNA stability in breast cancer and showing a pivotal role in anti-ferroptotic mechanism in that context." (PMID 41339932, 2025). "METTL3 and IGF2BP3 augment the resistance of breast cancer cells to doxorubicin (Dox) through the regulation of m6A modification of HYOU1." (PMID 39972939, 2025). "Subsequently, the ablation of Mettl3 impairs HR and leads to Adriamycin (ADR) chemo-sensitivity in breast cancer cells." (PMID 40242544, 2025). "Silencing METTL3 suppressed EMT by inhibiting MALAT1 expression, establishing the MALAT1/METTL3 axis of EMT in breast cancer." (PMID 40176927, 2024). "As m6A writers, METTL3 and WTAP can promote the Walburg effect of tumors, the former can promote both non-small cell lung cancer and breast cancer, and the latter can promote the progression of GC." (PMID 39033180, 2024). "Examples include the METTL3 inhibitor STM2457 in AML and cervical cancer, as well as CS1 and CS2 in AML and the FTO inhibitor 18097 in breast cancer." (PMID 39726589, 2024). "In breast cancer cells, peptidyl-prolyl cis-trans isomerase NIMA-interacting 1 (PIN1) interacts with METTL3 and prevents its ubiquitin-dependent proteasomal and lysosomal degradation." (PMID 38444581, 2024). "YTHDC1 binds to m6A-modified EGF mRNA and promotes EGF synthesis, suggesting that METTL3 and YTHDC1 together enhance HR and cell survival during doxorubicin treatment, leading to the development of drug resistance in breast cancer." (PMID 37264402, 2023). "To further confirm the relationship among METTL3, tumour growth and DOX sensitivity in human breast cancer, we generated a mouse xenograft model injected by MCF-7 cell line with the stable expression of METTL3 or a control vector." (PMID 36765397, 2023). "Here, we demonstrated that LATS1 mRNA m6A modification mediated by METTL3 and recognized by YTHDF2, plays a positive role in promoting both tumorigenesis and glycolysis in breast cancer." (PMID 36609396, 2023). "Knockout of the protein expression of METTL3 or YTHDF2 increased the expression of LATS1 mRNA and suppressed breast cancer tumorigenesis by activating YAP/TAZ in the Hippo pathway." (PMID 36609396, 2023). "A study reported that METTL3 regulates glycolysis by regulating m6A methylation of the key molecule of the Hippo pathway, LATS1, in breast cancer." (PMID 37684641, 2023). "We demonstrated that Mettl3-mediated m6A methylation of LATS1 mRNA is recognized by YTHDF2, which reduces LATS1 expression and inactivates the Hippo pathway in breast cancer." (PMID 36609396, 2023). "Mechanistically, the authors have shown that METTL3-mediated m6A modification of SOX2, one of the regulators of Nanog, promotes stemness and malignant progression of breast cancer." (PMID 37369946, 2023). "MCF7 and MDA-MB-231 exhibited increased METTL3 expression compared to MCF10-A, which was also observed in the broader panel of breast cancer cell lines with the exception of the Tamoxifen resistant cell line T47D1." (PMID 36725888, 2023).
breast cancer (continued). "Combined analysis of the multiple sequencing results revealed that METTL3 participates in the inhibition of LATS1 and affects tumorigenesis and metabolism in breast cancer cells." (PMID 36609396, 2023). "A recent study demonstrated that PD-L1 expression is positively correlated with the expression of METTL3 and IGF2BP3 in breast cancer." (PMID 36960074, 2023). "We found that the deletion of METTL3 significantly suppressed proliferation, migration, and invasion in MCF-7 and T47D breast cancer cells, as well as tumor progression in vivo." (PMID 36609396, 2023). "In this study, we have identified a cleaved form of METTL3, METTL3a (residues 239–580), that is essential for the METTL3–WTAP interaction, RNA m6A methylation, and breast cancer progression." (PMID 37589705, 2023). "The latest study showed that METTL3 promoted HR by regulating the EGF/RAD51 axis, leading to increased doxorubicin resistance in breast cancer cells." (PMID 37264402, 2023). "Therefore the potential dysregulation of other splicing factors and their subsequent splicing events still need to be explored, and this information might be particularly valuable to deepen our understanding of the biological relevance of METTL3 in breast cancer." (PMID 36725888, 2023). "MiR‐483p has been found to target METTL3 3′UTR to reduce the m6A level of p21, driving an antiproliferation effect in breast cancer." (PMID 36162823, 2023). "In this study, we investigated the direct relationship between ADAR1 and METTL3 and found that overexpression and knockdown of ADAR1 respectively increased and decreased the expression levels of METTL3 and ARHGAP5 protein in breast cancer." (PMID 36077054, 2022). "We observed that both ADAR1 and METTL3 are upregulated in breast cancer samples compared to normal controls, and ADAR1 positively correlated with METTL3 in TCGA data and in our study." (PMID 36077054, 2022). "METTL3 regulated MALAT1/E2F1/AGR2 pathway and subsequently controlled Adriamycin resistance in breast cancer." (PMID 36212476, 2022). "Positively controlled by METTL3, LINC00958 promotes the tumorigenesis for breast cancer by regulating the miR-378a-3p/YY1 axis." (PMID 35676619, 2022). "Another study found that METTL3 expression in breast cancer tissues is positively correlated with HBXIP expression and HBXIP is indeed a target of METTL3 methylation." (PMID 36008936, 2022). "We demonstrate that ADAR1 promotes the proliferation, migration and invasion of breast cancer cells through the METTL3/ARHGAP5/YTHDF1 axis and establish that METTL3 is one of the main targets of ADAR1 controlling biological functions." (PMID 36077054, 2022). "In this study, we found that METTL3, as an oncogene, is upregulated by ADAR1 in an RNA-editing dependent manner in breast cancer cell lines." (PMID 36077054, 2022). "PD-L1 expression was also positively correlated with METTL3 and IGF2BP3 expression in breast cancer tissues." (PMID 35197058, 2022). "We showed that overexpression and knockdown of ADAR1 increases and decreases METTL3 mRNA and protein levels in breast cancer cell lines, respectively, which indicates that ADAR1 positively correlates with METTL3." (PMID 36077054, 2022). "In breast cancer, METTL3 enhances the expression of HBXIP and induces positive feedback of HBXIP/let-7 g/METTL3/HBXIP signaling axis on cell proliferation." (PMID 35197058, 2022). "Low expression of METTL3, METTL14, WTAP and FTO was shown to correlate with relapse-free survival in breast cancer." (PMID 35721510, 2022). "In 2016, research showed that ZNF217 inhibited the m6A methylation of KLF4 and NANOG mRNA, which was catalyzed by METTL3 and resulted in elevated KLF4 and NANOG protein levels, which in turn promoted the progression of breast cancer." (PMID 35945641, 2022). "In most other cancer types, METTL3 functions as an oncogene, including AML, breast cancer, colorectal cancer, gastric cancer, liver cancer, lung cancer, pancreatic cancer and prostate cancer." (PMID 34895230, 2021).
breast cancer (continued). "These breast cancer patients with distinct molecular subtypes all represented lower expression of FTO, METTL3, and METTL14, and higher expression of YTHDF1 and YTHDF3 in tumor compared to the corresponding adjacent samples." (PMID 34804948, 2021). "In this study, the expression of m6A “writers” METTL3, METTL14, and “erasers” FTO were downregulated in 112 tumor samples compared to the paired normal controls based on TCGA breast cancer dataset." (PMID 34804948, 2021). "We then analyzed the expression profiles of circRNAs in breast cancer tissues by analyzing GEO database (GSE113230) and characterized a novel circRNA derived from the METTL3 gene, termed as circMETTL3." (PMID 33867838, 2021). "Methyltransferase METTL3 can enhance AK4 expression, increase the level of ROS in breast cancer cells and activate p38 Kinase, and promote the resistance of breast cancer to Tamoxifen, and the role of demethylation ALKBH5 is opposite to that of METTL3." (PMID 34484567, 2021). "Among them, the expression of RBM15, VIRMA, HNRNPA2B1, and YTHDF1/2/3 were significantly upregulated, but METTL3, METTL14, METTL16, WTAP, FTO, YTHDC1, and EIF3A had lower expression in breast cancer compared to normal samples." (PMID 34804948, 2021). "In breast cancer, METTL3 participates in a positive feedback loop comprising HBXIP/let-7g/METTL3/HBXIP that promotes proliferation." (PMID 33162550, 2020). "As to Mettl3, hepatitis B X-interacting protein (HBXIP) can increase its expression in breast cancer cells via inhibiting miRNA let-7g, which downregulated the expression of Mettl3 by targeting its 3′UTR50." (PMID 32444598, 2020). "In breast cancer (BC), HBXIP can upregulate METTL3 by suppressing miRNA let-7 g, and METTL3 promotes HBXIP expression through increased m6A modification, leading to an accelerated proliferation of BC cells." (PMID 32898471, 2020). "In this way, the positive feedback of HBXIP/let-7 g/METTL3/HBXIP is formed, which greatly accelerates the progression of breast cancer." (PMID 32612834, 2020). "Next, the effects of METTL3, METTL14, and FTO on distant metastasis free survival (DMFS) of total breast cancer patients and TNBC patients were analyzed using KM-plotter on-line database, respectively." (PMID 32766145, 2020). "Aberrant expression of m6A regulators, including METTL3, METTL14, WTAP, ALKBH5, and FTO, has been identified in breast cancer, as well as their potential prognostic values." (PMID 33585234, 2020). "In this study, by analyzing the prognostic role of m6A modulators (METTL3, METTL14, WTAP, FTO, and ALKBH5) in breast cancer using on-line databases, we found that only METTL3 played an important role in TNBC metastasis." (PMID 32766145, 2020). "METTL3, METTL16, ZC3H13, YTHDC1 and FTO were expressed at a low level in breast cancer, while KIAA1429, RBM15, and YTHDF1 were expressed at a high level." (PMID 33362863, 2020). "In breast cancer (BRC), by inhibiting let-7g to upregulate METTL3, HBXIP forms a positive feedback loop of HBXIP/let-7g/METTL3/HBXIP, leading to accelerated proliferation of breast cancer cells." (PMID 32547941, 2020). "These researchers also noted that METTL3 and METTL14 were upregulated in the normal breast-like and luminal breast cancer subtypes compared with the basal-like and HER2-overexpressing types." (PMID 31921660, 2019). "In addition, the “writers” METTL3 and METTL14 were more predisposed to mutation or CNV than the other genes in ccRCC, while alterations of the “erasers” FTO and ALKBH5 were proved to be more important in breast cancer, glioblastoma and hematological malignancies." (PMID 30877265, 2019). "Our findings differ from previous reports that have shown total RNA m6A levels in breast cancer cell lines decrease in hypoxia conditions through HIF mediated induction of the demethylase ALKBH5 and/or METTL3 sequestration by ZNF217." (PMID 30131850, 2018).